ALG10 (ALG10 alpha-1,2-glucosyltransferase)
Description:
Dol-P-Glc:Glc(2)Man(9)GlcNAc(2)-PP-Dol alpha-1,2-glucosyltransferase that operates in the biosynthetic pathway of dolichol-linked oligosaccharides, the glycan precursors employed in protein asparagine (N)-glycosylation. The assembly of dolichol-linked oligosaccharides begins on the cytosolic side of the endoplasmic reticulum membrane and finishes in its lumen. The sequential addition of sugars to dolichol pyrophosphate produces dolichol-linked oligosaccharides containing fourteen sugars, including two GlcNAcs, nine mannoses and three glucoses. Once assembled, the oligosaccharide is transferred from the lipid to nascent proteins by oligosaccharyltransferases. In the lumen of the endoplasmic reticulum, adds the third and last glucose residue from dolichyl phosphate glucose (Dol-P-Glc) onto the lipid-linked oligosaccharide intermediate Glc(2)Man(9)GlcNAc(2)-PP-Dol to produce Glc(3)Man(9)GlcNAc(2)-PP-Dol.
Synonyms: ALG10A; FLJ14751; DIE2; KCR1
Tractability: Antibody: UniProt predicts a signal peptide or a membrane-spanning region. PROTAC: ubiquitination databases record sites on it.
Safety:
Unwanted effects reported when the protein is acted on. In parentheses: how it was acted on, where the effect was seen, and who reports it.
drug toxicity (source: ClinPGx)
Gene: Protein-coding gene on chromosome 12 (34,022,468 to 34,029,694, forward strand). Ensembl gene ENSG00000139133.
Subcellular location: Endoplasmic reticulum membrane
Subcellular location (Human Protein Atlas): Endoplasmic reticulum
Pathways (Reactome):
Metabolism of proteins: Biosynthesis of the N-glycan precursor (dolichol lipid-linked oligosaccharide, LLO) and transfer to a nascent protein
Gene Ontology:
Molecular function: protein binding; dolichyl pyrophosphate Glc2Man9GlcNAc2 alpha-1,2-glucosyltransferase activity
Biological process: dolichol-linked oligosaccharide biosynthetic process
Cellular component: endoplasmic reticulum membrane
Genetic constraint (gnomAD): Loss-of-function variants: 25 observed, 38.75 expected, observed/expected ratio (o/e) 0.65, 90% interval 0.47 to 0.9. The upper end of that interval is the gene's LOEUF score, 0.9, which puts it in group 3 of 6, group 1 being the genes least tolerant of losing a copy. Missense variants: 486 observed, 562.49 expected, observed/expected ratio (o/e) 0.86, 90% interval 0.8 to 0.93. Synonymous variants: 184 observed, 202.36 expected, observed/expected ratio (o/e) 0.91, 90% interval 0.81 to 1.03.
Gene-disease validity (ClinGen):
ClinGen rates the evidence that ALG10 causes each of these diseases.
congenital disorder of glycosylation (autosomal recessive): Limited. Congenital disorder of glycosylation (CDG) is a fast growing group of inborn errors of metabolism characterized by defective activity of enzymes that participate in glycosylation (modification of proteins and other macromolecules by adding and processing of oligosaccharide side chains).
Homologues: Orthologues: chimpanzee ALG10 (99% identical), macaque ALG10 (97% identical), rat Alg10 (87% identical), mouse Alg10b (86% identical), tropical clawed frog alg10 (57% identical), zebrafish alg10 (56% identical), Drosophila melanogaster Alg10 (32% identical), Caenorhabditis elegans algn-10 (30% identical). Paralogues in human: ALG10B (96% identical).
Diseases named in the same sentence as ALG10 in open-access papers:
ALG10 is named in the same sentence as 11 diseases in open-access papers, as found by Europe PMC text mining. Sharing a sentence is not in itself a finding about the gene and the disease. The quoted sentences say what the papers report.
colorectal cancer (2 papers, 2022 to 2023). A primary or metastatic malignant neoplasm that affects the colon or rectum. "Here, we screened 12 ALGs’ expression through online datasets and found that ALG10 was mostly upregulated in colorectal cancer tissues." (PMID 35680565, 2022). "This work identified a novel ALG10/TGF-β positive regulatory loop responsible for colorectal cancer stemness." (PMID 35680565, 2022). "In vivo tumorigenic analysis indicated that ALG10 knockdown attenuated the tumor-initiating ability and chemoresistance of colorectal cancer cells." (PMID 35680565, 2022). "An article published recently concluded that high expression of ALG10 facilitated the glycosylation of TGFBR2, stimulated TGF-β pathway and thus promoted the stemness of colorectal cancer cells." (PMID 36879254, 2023).
Arrhythmia (1 paper, 2022). Any cardiac rhythm other than the normal sinus rhythm. "ALG10 has been shown to be necessary for efficient N-glycosylation and leaf growth, and it has been demonstrated that ALG10 is associated with arrhythmia." (PMID 35680565, 2022).
cholangiocarcinoma (1 paper, 2025). A carcinoma that arises from the intrahepatic biliary tree (intrahepatic cholangiocarcinoma) or from the junction, or adjacent to the junction, of the right and left hepatic ducts (hilar cholangiocarcinoma). "For example, distinct peptide mass fingerprints (PMFs) were identified for early versus late recurrence in cholangiocarcinoma (CCA), where peptides such as KNTC1, DCLK1, ALG10, ATR, and BLM were associated with early recurrence, while SERPINA1, TGFB2, and SERPING1 were implicated in late recurrence." (PMID 41008874, 2025).
metabolic (1 paper, 2011). "As the glycosylation process seems to be conserved in higher eukaryotes our data suggest that a similar ALG10 defect in mammals should also lead to drastic protein hypoglycosylation resulting in severe metabolic diseases or developmental changes in other organisms." (PMID 21707802, 2011).
progressive myoclonus epilepsies (1 paper, 2025). "ALG10 has recently been associated with progressive myoclonus epilepsies." (PMID 39482899, 2025). "ALG10 has been recently associated with progressive myoclonus epilepsies." (PMID 39482899, 2025).
rectal cancer (1 paper, 2023). A primary or metastatic malignant neoplasm that affects the rectum. "Future articles in this series will go into more details about the effects of hub genes of PLAGL2, ZNF337 and ALG10 on the phenotype of rectal cancer cells after irradiation in vitro and in vivo." (PMID 36879254, 2023). "However, the role of ALG10 in chemoradiotherapy resistance of rectal cancer had not been rigorously studied and discussed." (PMID 36879254, 2023).
tumor (2 papers, 2022 to 2023). "Analysis based on exploration of the clinical predictive value showed PLAGL2, ZNF337 and ALG10 were significantly associated with tumor immune infiltration, different immune-related genes and sensitivity of chemotherapeutic drugs." (PMID 36879254, 2023). "In consistent, ALG10 knockdown-mediated decrease of tumor-initiating ability was rescued by TGFBR2 treatment." (PMID 35680565, 2022). "We found that the tumorigenic ability of CRC cells with ALG10 knockdown was decreased, which was evident by the decreased tumor-formation rate and stem cell frequency using the tumor-limiting dilution assay." (PMID 35680565, 2022). "A nomogram was constructed using the TCGA READ dataset based on the expression of ALG10, PLAGL2 and ZNF337 and the clinical characteristics including age, gender, stage, tumor (T), lymph node (N) and metastasis (M) stage." (PMID 36879254, 2023). "We tried to detect the effects of ALG10 on the tumor-initiating ability of CRC cells, which is positively correlated the stemness of tumor cells." (PMID 35680565, 2022). "As several lines of evidence have demonstrated the critical role of TGF-β pathway in the maintenance of tumor stemness and ALG3, another ALG family member, has recently been reported to enhance TGFBR2 glycosylation, we wondered whether ALG10 held the similar effects on TGFBR2 with ALG3." (PMID 35680565, 2022).
ALG10 also shares sentences with these, for which no sentence is quoted: autoimmune disease (1 paper); cancer (1); Obesity (1); type 2 diabetes mellitus (1).